NDRG1 (N-myc downstream regulated 1)
Diseases named in the same sentence as NDRG1 in open-access papers (continued):
Sharing a sentence is not in itself a finding about the gene and the disease.
breast carcinoma (continued). "In the context of breast cancer, NDRG1 appears to be multifaceted, as it has been proposed to act as a promoter of tumor growth and brain metastasis in some cases of estrogen receptor–negative (ER-negative), aggressive breast cancers." (PMID 37847564, 2023). "N-myc downstream-regulated gene-1 (NDRG1) is well-described as a potent metastasis suppressor, but its role in human breast cancer remains controversial and unclear." (PMID 37858101, 2023). "Firstly, the expression of the NDRG1 concerning breast cancer metastasis was investigated by researchers, and there were a limited number of studies that provided evidence of NDRG1 protein expression in patients with breast cancer." (PMID 37858101, 2023). "Further studies are crucially needed to investigate the expression of NDRG1 protein concerning breast cancer metastasis." (PMID 37858101, 2023). "In breast cancer cells, upon reoxygenation, NDRG1 expression is significantly reduced while c-Myc protein expression is upregulated." (PMID 37345116, 2023). "More recently, NDRG1 has emerged as a potential target for therapy and a predictive biomarker in aggressive breast cancers, as it significantly correlates with worse clinical outcomes." (PMID 37858101, 2023). "NDRG1 is a stress response gene involved in regulating the response to surgical stress in breast cancer cells." (PMID 37395734, 2023). "Breast cancer exemplifies this dichotomy, in which NDRG1 suppresses metastasis in ER-positive subtypes and promotes tumor progression in aggressive forms of breast cancer, such as TNBC 9,14-18,26." (PMID 36594086, 2023). "NDRG1 has been reported to act as a metastasis suppressor in multiple human cancers, including breast cancer." (PMID 37847564, 2023). "It was observed, in comparison to normal breast tissues, there was a significant increase in the CD24 and NDRG1 expression in breast cancer." (PMID 37842046, 2023). "The dual role of NDRG1 as a metastasis/tumor progressor or suppressor has been reported in breast cancer 9,14-18." (PMID 36594086, 2023). "Reports also indicated decreased expression of ErbB receptors such as EGFR, HER2, and HER3 to NDRG1 expression preventing the formation of HER2/HER3 dimers and disrupting major oncogenic pathways primarily associated with mammary tumors." (PMID 37970212, 2023). "NDRG1 reflects neutral lipid metabolism thus promoting breast cancer proliferation, and the mRNA expression is relatively higher in TNBC cells." (PMID 35459269, 2022). "NDRG1 expression was investigated in breast cancer (BCa) samples and was reported to be an independent prognostic factor." (PMID 36497221, 2022). "Though these studies established NDRG1 to be a promising target for regulating BCa progression, its role in breast cancer remains controversial due to it also being involved in metastasis progression." (PMID 36497221, 2022). "The results of the downregulation on NDRG1 by the ectopic overexpression of WISP1v1 are in agreement with a previous study in breast carcinoma cells." (PMID 36232736, 2022). "NDRG1 has been described as a potent metastasis suppressor in a number of tumors, e.g., colon, prostate, and breast cancers." (PMID 36160437, 2022). "NDRG1 has been shown to be involved in lipid metabolism in breast cancer cell lines, aiding in cell survival in lipid poor environments." (PMID 36213122, 2022). "Previous research also indicated that mRNA expression of NDRG1 is relatively higher in TNBC than that in other types of breast cancer cells." (PMID 35459269, 2022). "Dp44mT exhibits anticancer activity in a number of cancers, such as leukemia, neuroblastoma, oral, lung, prostate and breast cancer, by promoting apoptosis, inducing cell cycle arrest and upregulating the expression of NDRG1." (PMID 34413268, 2021). "Like PROM1 and KLK7, NDRG1 is most highly expressed in basal breast cancers; yet, when expressed in ER-positive primary tumors, NDRG1 confers significantly worse disease-specific survival outcomes." (PMID 33407744, 2021).
breast carcinoma (continued). "NDRG1 expression was found to be increased after treatment with 5-Aza-Dc in breast cancer, prostate cancer and pancreatic cancer." (PMID 34616614, 2021). "NDRG1 has been reported to regulate the fate of lipid in cells with altered lipid metabolism, thus contributing to breast cancer aggressiveness." (PMID 33808259, 2021). "Nevertheless binding to the Pten promoter, previously reported in muscle, was confirmed, and the reported binding of Tbx2 to the proximal promoter of Ndrg1 in breast cancer cells was also found, although with additional sites occupied within the first intron." (PMID 34819350, 2021). "We acknowledge the limited nature of this study, but feel that it provides useful supportive data for understanding the role of NDRG1 in breast cancer." (PMID 32612361, 2020). "NDRG1 is widely known as a metastasis suppressor in breast cancer, acting mainly by suppressing migration and invasion of breast cancer cells." (PMID 33321961, 2020). "NDRG1 had the greatest fold change in cybrids and was also observed to be amplified and overexpressed in a substantial proportion of breast cancer patient samples." (PMID 32612361, 2020). "The induction of NDRG1 was shown in a mouse mammary tumor model to suppress metastasis by modulating WNT pathway signaling." (PMID 33321961, 2020). "Breast cancer patients with bone metastasis presented with reduced expression of NDRG1 and their survival was also influenced by NDRG1 expression." (PMID 31213036, 2019). "Evidences have demonstrated that NDRG1 expression was significantly decreased in several malignant diseases, including gastric, colorectal, prostate, and breast cancer." (PMID 31831018, 2019). "This indicates that NDRG1 regulates neutral lipid storage in SKBR3 cells and that NDRG1-dependent lipid homeostasis in breast cancer cells is important for optimal cell viability." (PMID 29898756, 2018). "In line with its role in promoting myelination and its association with altered metabolism in cancer, our findings show that NDRG1 is a critical regulator of lipid fate in breast cancer cells." (PMID 29898756, 2018). "NDRG1 as a prognostic factor in breast cancer remains controversial, as it continues to be cited as both a biomarker of negative prognosis and as a metastasis suppressor." (PMID 29898756, 2018). "Here we report that NDRG1 contributes to breast cancer aggressiveness by regulating the fate of lipids in cells that exhibit an altered lipid metabolic phenotype." (PMID 29898756, 2018). "Because NDRG1 copy number or mRNA expression is altered in approximately 25% of all breast cancers in the The Cancer Genome Atlas (TCGA) data set, patients in the upper quartile of NDRG1 mRNA expression were compared with patients in the lower three quartiles." (PMID 29898756, 2018). "Since the role of NDRG1 in altered cancer metabolism is poorly characterized, in vitro studies of NDRG1 were carried out in a range of breast cancer cell lines to assess its function." (PMID 29898756, 2018). "Proteins negatively correlated with phospho-NDRG1 mirrored the results of the mRNA associations, as did an analysis of mRNA levels in NDRG1 altered and unaltered cases, corroborating a link between NDRG1 and aggressive forms of breast cancer." (PMID 29898756, 2018). "SGK1, when overexpressed in PR-positive T47D and PR-negative MDA-MB-231 breast cancer cells, mimicked the effect of progesterone by up-regulating the expression of NDRG1, which in turn led to a significant reduction in cell migration and cell invasion." (PMID 30337371, 2018). "Elevated N-myc downstream regulated gene (NDRG1) messenger RNA (RNA) and protein expression is found in a subset of many solid tumors, including breast cancer." (PMID 29898756, 2018). "The top downregulated gene in NDRG1 knockdown cells was Spot14, which plays an incompletely understood regulatory role in stimulating the lipid synthetic process in breast cancer cells." (PMID 29898756, 2018).
breast carcinoma (continued). "The central role of NDRG1 in regulating fatty acid metabolic fate, neutral lipid storage, and cell viability in breast cancer cells establishes strong evidence of its function in cancer cell metabolism." (PMID 29898756, 2018). "Several lines of evidence show that NDRG1 performs an important pro-survival function in regulating the fate of lipids in breast cancer cells." (PMID 29898756, 2018). "This meta-analysis significantly strengthens the link between elevated NDRG1 expression and poor prognosis in breast cancer." (PMID 29898756, 2018). "Here, we show that NDRG1 is expressed in a Warburg-like metabolic gene expression program common to many solid tumors, including breast cancer." (PMID 29898756, 2018). "We found that NDRG1, in turn, inactivates a set of kinases, impeding the invasion and migration of breast cancer cells." (PMID 30337371, 2018). "Taken together, these results indicate that NDRG1 function influences pathways dictating the flow of fatty acids into storage and structural lipid pathways in breast cancer cells." (PMID 29898756, 2018). "In breast cancer, the interaction of TBX2 with EGR1 represses the putative breast tumor suppressor, NDRG1 (N-myc downregulated gene 1), which is implicated in cell differentiation, apoptosis and senescence." (PMID 29719592, 2018). "Positive correlation was common between NDRG1 and genes associated with angiogenesis, glycolysis, hypoxia, and basal cell lineage, illustrating that high NDRG1 expression is more common in ER− breast cancers." (PMID 29898756, 2018). "Archived mammary tissue specimen blocks of breast cancer patients who received weekly paclitaxel in a single centre were retrieved and NDRG1 immunohistochemistry was performed on normal nerve tissue found within the sample." (PMID 27716814, 2016). "Previously, we showed that NDRG1 plays a role in tumor adaptation to the fluctuation of oxygen concentrations in MCF-7 breast cancer cells." (PMID 26852918, 2016). "In this study, we demonstrated that AHR directly up-regulates NDRG1 under hypoxia in MCF-7 breast cancer cells." (PMID 26852918, 2016). "Consistent with this, extremely high doses of 100 μM EMD638683 are required to observe marginal reduction in NDRG1 phosphorylation in breast cancer cells that express high levels of SGK1 (Eeva Sommer, data not shown)." (PMID 27481935, 2016). "In breast cancer cells, forced overexpression of NDRG1 has been demonstrated to repress cell proliferation and invasion." (PMID 25732125, 2015). "NDRG1 knock down using shRNA increased MCF-7 cell proliferation and invasion, indicating that NDRG1 functions as a tumor suppressor gene for breast cancer, as previously reported." (PMID 25732125, 2015). "Further, we demonstrated for the first time the mechanisms by which WISP1 modulates NDRG1 expression in human breast cancer cells." (PMID 25732125, 2015). "For example, ectopic overexpression of NDRG1 in MDA-MB-468 breast cancer cells is reported to suppress in vitro invasiveness and ectopic overexpression of NDRG1 in cultured MCF-7 breast cancer cells is reported to suppress proliferation rate." (PMID 23581296, 2013). "The methylation status in the breast tumor samples was also detected and the association with the clinicopathological data was analyzed to further explore the relationship between the methylation status of NDRG1 gene and the development of breast cancer." (PMID 23899187, 2013). "Using bisulfite sequencing, as well as nested-methylation-specific PCR (nested-MSP), we further analyzed the different NDRG1 methylation status in these two breast cancer cell lines." (PMID 23899187, 2013). "The results of the present study showed that in 87 breast cancer samples, NDRG1 transcripts were greatly depressed compared with corresponding normal tissues (p = 0.000)." (PMID 23899187, 2013).
breast carcinoma (continued). "Although decreased NDRG1 expression has been described in a number of tumour types, including breast cancer, increased NDRG1 expression has also been described in a number of cancers." (PMID 23581296, 2013). "NDRG1 is down-regulated in colon cancer, prostate cancer, and glioma, while is up-regulated in breast cancer, liver cancer, and lung cancer." (PMID 24269992, 2013). "It is proposed that NDRG1 promoter demethylation and the restoration of NDRG1 expression has potential therapeutic use for breast cancer." (PMID 23899187, 2013). "To confirm the epigenetic transcriptional silencing of NDRG1 in breast cancer, we treated the T47D cell line with demethylating the agent AZA at 0, 2.5, 5 and 10 μM concentrations, respectively." (PMID 23899187, 2013). "Of the 389 incidence breast cancer cases from a large number of populations in Qingdao, China, the methylat-ion of NDRG1 was detected in 121 cases (31.1%) showing CpG methylation in the region evaluated by nested-MSP." (PMID 23899187, 2013). "In the present study, we first analyzed the expression of NDRG1 in 87 fresh frozen breast tumors, corresponding normal tissues and breast cancer cell lines." (PMID 23899187, 2013). "In recent years, NDRG1 has been described as a potential tumor suppressor gene in various human cancers, including breast cancer." (PMID 23899187, 2013). "In the present study, we first examined the relationship between the methylation status of the NDRG1 gene promoter and its steady-state expression in breast tumors, corresponding normal tissues and two breast cancer cell lines." (PMID 23899187, 2013). "Previous studies have shown that NDRG1 expression is down-regulated in various cancer tissues, such as colon, prostate, and breast cancer tissues." (PMID 23899187, 2013). "It has also been shown that expression of NDRG1 is downregulated upon estradiol stimulation, and its expression is correlated with favorable prognosis in breast cancer patients." (PMID 23227362, 2012). "Recently, It was reported that NaBu induces breast cancer cell differentiation by regulating β-casein and N-myc downstream-regulated gene 1 (NDRG1) in breast cancer cells." (PMID 22253909, 2012). "An oncogenic and tumor-promoting role of NDRG1 has also been reported, because it was overexpressed in various human cancers, including lung, brain, skin, kidney, and breast cancers." (PMID 21912630, 2011). "NDRG1 not only plays an important role in metastatic tumor progression, it has also been observed to slow the advancement of breast cancer in a clinical study and, interestingly, to be regulated by PTEN through an Akt-dependant pathway." (PMID 20205716, 2010). "Immunohistochemical examination of the tissue from 29 patients with prostate cancer and 33 patients with breast cancer, demonstrated in 7 there was high NDRG1 levels in normal prostate and breast epithelium, whereas a significant down-regulation was observed in high-grade cancers." (PMID 40378957, 2025). "Given that NDRG1 significantly promotes tumor progression and brain metastasis in aggressive breast cancer, NSUN6 may potentially co-drive breast cancer radioresistance via NDRG1 regulation." (PMID 40823093, 2025). "A recent investigation has also confirmed that NDRG1 hyperexpression is pro-oncogenic in aggressive ER-negative breast cancer, with higher nuclear NDRG1 localization being detected in brain metastatic tumors relative to primary breast cancer." (PMID 40378957, 2025). "Furthermore, studies on breast cancer (BC) have shown an inverse correlation between NDRG1 expression and estrogen receptor-alpha (ER-α) expression." (PMID 40332138, 2025). "On the other hand, NDRG1 overexpression of full-length NDRG1 provided resistance in ER + breast cancer cells against mitoDFX, which suggests that high expression of NDRG1 might modulate response to the treatment and cause resistance." (PMID 38983911, 2024).
breast carcinoma (continued). "Interestingly, NDRG1 expression is also involved in the differentiation of breast cancer cells in vitro and in vivo: overexpression of NDRG1 in MDA-MB-231 cells led to increased areas of well-differentiated tumors in xenograft mouse models." (PMID 38611020, 2024). "Notably, NDRG1 is highly amplified in breast cancer, particularly in basal-like and metastatic breast cancers." (PMID 38611020, 2024). "Thus, we examined the role of NDRG1 overexpression in influencing the invasion index of the breast cancer cells since tumors become more malignant in hypoxia and NDRG1 expression is dependent on hypoxia." (PMID 38983911, 2024). "High NDRG1 expression and also an absence of expression were associated with worse survival outcomes in both breast cancer and breast cancer brain metastasis patients." (PMID 40530439, 2024). "Therefore, we next examined the phosphorylation of NDRG1 at these two sites by immunoblotting in breast cancer and fibroblast cells." (PMID 38983911, 2024). "We then explored whether the increased levels of full-length NDRG1 modulate the response to iron chelation in breast cancer cells." (PMID 38983911, 2024). "However, none of these studies have included in vivo experiments to confirm the in vitro findings on the proliferation and migration/invasion of NDRG1-high vs. NDRG1-low cells, and only two studies have reported outcomes from patients with breast cancer." (PMID 38611020, 2024). "However, recent findings challenge this perception, particularly for NDRG1, which has demonstrated a critical role in driving tumor growth and metastasis in aggressive forms of breast cancer." (PMID 38611020, 2024). "However, mRNA levels of NDRG1 varied across the three breast cancer lines, being up-regulated in MDA-MB-231 cells and down-regulated in HCC1954 and MCF-7 cells." (PMID 37842046, 2023). "Using a random-effects model, the pooled log odds ratio of effect estimate was used to look at the link between NDRG1 protein expression and aggressive features of breast cancer, such as tumor grade, tumor stage, metastasis to the axillary lymph nodes, and hormonal receptor status." (PMID 37858101, 2023). "For instance, cophosphorylation of Serum/glucocorticoid-regulated kinase 3 (SGK3) with GSK-3β enhances the binding of FBXW7 to metastasis suppressor N-Myc downstream regulated gene 1 (NDRG1) and promotes NDRG1's ubiquitination, increasing breast cancer invasion and metastasis." (PMID 37658431, 2023). "Moreover, another study has revealed methylation of the NDRG1 promoter in about one third of primary breast cancer specimens." (PMID 37249826, 2023). "Similarly, high NDRG1 expression was correlated with tumor progression and brain metastasis in patients with aggressive breast cancer, and it was suggested that the upregulation of NDRG1 had worse clinical outcomes." (PMID 37759706, 2023). "Similarly, gene sets analysis by GOBO online tool showed that the higher NDRG1 gene expression, the poorer relapse-free survival in all cases of breast cancer (p=0.003) and basal subtype (p=0.002)." (PMID 36594086, 2023). "Although the postulated function of NDRG1 as a suppressor of breast cancer metastasis and other cancers exists, the relevance of NDRG1 in human breast cancer remains uncertain and speculative." (PMID 37858101, 2023). "Furthermore, IHC results from the HPA database demonstrated that NDRG1 protein expression was higher in breast cancer tissues." (PMID 37842046, 2023). "Several studies have demonstrated that NDRG1 acts as a tumor and metastasis suppressor, exhibiting pleiotropic activity in various types of tumors, including colorectal cancer, lung cancer, esophageal squamous cell carcinoma, and breast cancer." (PMID 37858101, 2023). "Despite the development of NDRG1 up-regulators (such as the di-2-pyridylketone thiosemicarbazone class), further studies are required to clarify the exact role of this protein in breast cancer progression." (PMID 37759706, 2023).